CASP2 (caspase 2)
Diseases named in the same sentence as CASP2 in open-access papers (continued):
Sharing a sentence is not in itself a finding about the gene and the disease.
lung carcinoma (14 papers, 2012 to 2026). "It is proposed that this failure to arrest is what leads to the enhanced polyploidy seen in caspase-2-deficient lung cancer cells." (PMID 33425918, 2020). "Similarly, loss of caspase-2 has been linked to increased tumor burden in the Kras-driven lung cancer model." (PMID 33425918, 2020). "It is well known that caspase-2 acts as a tumor suppressor in many cancers, including lung cancer, whereas p62 overexpression and/or its reduced degradation is commonly associated with tumor formation, cancer promotion, and resistance to therapy." (PMID 39543123, 2024). "TRAF2 mediates apoptosis in breast, cervical, and lung cancer cells by stabilizing the caspase-2 dimer complex and enhancing its activity to fully commit the cell to death, according to prior research." (PMID 35631261, 2022). "For instance, ATM deficient or constitutive Myc proto-oncogen expressing mice lacking caspase-2 develop lymphoma with significantly higher incidence and rate, whereas Kras expressing mice develop lung cancer with increased incidence when caspase-2 is depleted." (PMID 35444189, 2022). "We therefore studied the effect of NVP-BEZ235 on PARP cleavage and caspase-2 activation in two most sensitive lung cancer cell lines, HCC2935 and H2170." (PMID 22355357, 2012). "There was a study showing that E2F1 negatively regulates CASP2 expression in lung carcinoma cells." (PMID 39524140, 2024). "Recent studies have indicated that caspase-2 acts as a tumor suppressor in Kras-driven lung cancer." (PMID 25980443, 2015).
lymphoma (13 papers, 2010 to 2026). A malignant (clonal) proliferation of B- lymphocytes or T- lymphocytes which involves the lymph nodes, bone marrow and/or extranodal sites. "On the contrary, mouse embryonic fibroblasts (MEFs) with caspase-2 knockout showed a higher proliferation rate, and the mouse Eμ-Myc lymphoma model with loss of caspase-2 showed accelerated tumorigenesis." (PMID 39625520, 2024). "The tumor-suppressive function of caspase-2 was reported in a Eμ-Myc mouse model, in which loss of either a single or both alleles of caspase-2 resulted in accelerated lymphoma tumorigenesis." (PMID 34069817, 2021). "Incidence of both low and high grade aneuploidy was increased in dual Casp2/Atm-deficient lymphomas, suggesting that caspase-2 protects against aneuploidy." (PMID 33425918, 2020). "As loss of Caspase-2 leads to an acceleration of tumor onset in the Eμ-Myc mouse lymphoma model, whereas loss of Pidd1 actually delays onset of this disease, we set out to interrogate the role of Raidd in cancer in more detail." (PMID 25857265, 2015). "In the case of Casp2, this has been best demonstrated in the Eu-myc lymphoma model, where loss of even a single copy of Casp2 can accelerate malignant transformation." (PMID 21573140, 2011). "When caspase-2-deficient Eμ-myc compound mice were generated, lymphoma development turned out to be accelerated." (PMID 24281211, 2010). "Interestingly, deficiency in only one caspase-2 allele was sufficient to promote lymphoma development indicating that caspase-2 might be a haploinsufficient tumor suppressor gene." (PMID 24281211, 2010). "Although the mechanism underlying c-Myc induced caspase-2-mediated tumor suppression remains to be elucidated, previous in vivo studies also give strong evidence for the involvement of caspase-2 in tumor suppression in Eμ-Myc mouse lymphoma model." (PMID 32438737, 2020). "The first demonstration of the tumor suppressor ability of caspase-2 was in an Eμ-Myc model of lymphoma." (PMID 33425918, 2020). "Atm-deficient lymphomas display a low level of chromosomal instability, but this was significantly exacerbated in the absence of caspase-2." (PMID 33425918, 2020). "In Atm-deficient lymphomas, loss of caspase-2 conferred a proliferative advantage without impacting apoptosis." (PMID 33425918, 2020). "In addition, reduced CASP2 expression has been reported in lymphoma and leukemia and correlates with poor prognosis in AML and ALL25,26." (PMID 30670683, 2019). "While the specific and diverse functions of Rap1 are context dependent, a role for caspase-2 in regulating Rap1 signaling is highly relevant to lymphoma onset and progression and will be important to further define the contributing roles of Rap1 and caspase-2 in B-cell lymphomagenesis." (PMID 30670683, 2019). "All pathways were significantly enriched when analyzed using GSEA, suggesting that caspase-2 may have a role in regulating T-cell signaling and/or Rap1 signaling to influence lymphoma development in EμMyc mice." (PMID 30670683, 2019). "Macroscopic examination identified other common age-related tumors at low incidence in both WT and caspase-2-deficient mice, including abnormal sarcoma-like lumps (nonspecified on limbs), thymomas, lymphomas, and ovarian tumors; however, these were not further characterized histologically." (PMID 41477850, 2026). "In contrast, sub-cultured primary lymphoma cells from Eμ-Myc lymphomas lacking caspase-2 showed a decreased sensitivity to apoptosis induced by cytoskeletal disruption and irradiation as measured by Annexin V binding." (PMID 33425918, 2020).
Alzheimer disease (9 papers, 2016 to 2024). A progressive, neurodegenerative disease characterized by loss of function and death of nerve cells in several areas of the brain leading to loss of cognitive function such as memory and language. "Caspase-2 has also been implicated in pathologies associated with neurodegenerative disorders such as Huntington’s disease, Alzheimer’s disease and aging." (PMID 32038563, 2019). "Recently, a soluble form of tau, Δtau314, which is generated when caspase-2 (Casp2) cleaves tau at Asp314, was reported to be associated with impaired cognition in mice modeling frontotemporal dementia, and with mild cognitive impairment and Alzheimer’s disease (AD) in humans." (PMID 31362787, 2019). "Some of these interesting genes, such as MAPT, CASP2, and PSEN2, are linked with important aspects of Alzheimer’s disease, such as dementia, increase cell death, and deposition of amyloid-beta proteins in Alzheimer’s disease brains." (PMID 27901073, 2016). "Caspase-2 is a member of the caspase family that exhibits both apoptotic and non-apoptotic properties, and has been shown to mediate synaptic deficits in models of several neurological conditions, including Alzheimer’s disease (AD), Huntington’s disease (HD), and Lewy Body dementia (LBD)." (PMID 36129947, 2022). "Caspase-2 (Casp2) is a promising therapeutic target in several human diseases, including nonalcoholic steatohepatitis (NASH) and Alzheimer’s disease (AD)." (PMID 36379916, 2022).
leukemia (9 papers, 2011 to 2024). A malignant (clonal) hematologic disorder, involving hematopoietic stem cells and characterized by the presence of primitive or atypical myeloid or lymphoid cells in the bone marrow and the blood. "RPMI8226 cells were the most sensitive to increased caspase 2 activity after longer incubation with all tested derivatives when compared to both leukemia cell lines." (PMID 36430734, 2022). "In contrast, increased levels of the total MHC class II protein was evident in protein lysates from caspase-2 RNAi-silenced leukemia cell lines and B-cells isolated from gene-targeted mice." (PMID 29362422, 2018). "Additional studies will be important to determine the molecular pathway by which caspase-2 regulates HSC and progenitor genomic stability and differentiation, and to assess any increase in susceptibility of aged Casp2−/− mice to leukaemia." (PMID 27906175, 2016). "Indeed, our current studies demonstrate that GSK-3β mediates ER stress-induced lysosomal apoptosis in leukemia involving caspase-2-induced LMP and cathepsin B relocation, which result in caspase-8 and -3 activation." (PMID 26727221, 2016). "In leukemia, this drug induces mitotic catastrophe in chronic myelogenous leukemia (CML) cells via JNK-dependent inhibition of Plk1 expression and triggers apoptosis by a caspase 2-mediated mechanism." (PMID 35734412, 2022).
melanoma (8 papers, 2007 to 2024). A malignant, usually aggressive tumor composed of atypical, neoplastic melanocytes. "In this study we demonstrated that Phenoxodiol treatment of melanoma cells also caused XIAP degradation, cleavage of pro-caspase-2, and activation of caspases -3, -8 and -9 in Carboplatin resistant melanoma cell lines." (PMID 17257402, 2007). "In melanoma cells resistant to other therapies, such as docetaxel, caspase-2 can activate the mitochondrial apoptotic pathway, including the pro-apoptotic protein Bax." (PMID 39329914, 2024). "On the other hand, the Caspase-14, Caspase-7, and Caspase-2 genes revealed decreased mRNA levels in response to UA treatment in A-375 melanoma cells, although these decreases were statistically insignificant (p < 0.05)." (PMID 39473730, 2024). "Our study provides novel insights into how caspase-2 accomplishes its tumor suppressor function in human carcinoma and melanoma cells, involving p54nrb as a key regulatory factor." (PMID 35444189, 2022). "Several studies with human prostate cancer cells, human melanoma cells and mouse embryonic fibroblasts have shown that caspase-2 is required for apoptosis induction by taxanes." (PMID 23672670, 2013). "Caspase-2 plays a pivotal role in apoptosis initiation, particularly in melanoma." (PMID 39329914, 2024). "Among these, caspase-2 is known to initiate apoptosis and may trigger a caspase cascade, leading to cell death in melanoma." (PMID 39329914, 2024). "This suggests that caspase-2 regulation is crucial for the effectiveness of IFN-beta therapy and could potentially enhance melanoma cell sensitivity to chemotherapy." (PMID 39329914, 2024).
Cognitive impairment (7 papers, 2011 to 2022). Abnormal cognition is characterized by deficits in thinking, reasoning, or remembering. "Strikingly, a recent study on human individuals suffering from AD found that the levels of Δtau314 correlate with cognitive impairment, and also caspase-2 protein levels were increased in these patients, confirming the findings made in mouse models." (PMID 32415279, 2020). "First, that the levels of both Casp-2 and Δtau314 proteins in the CI individuals are higher than in the CN individuals and that levels of Δtau314 proteins moderately predict cognitive impairment are correlative findings." (PMID 32123248, 2020). "Rather, they suggest that Casp-2 and Δtau314 proteins are potentially involved in molecular pathways that lead to cognitive impairment." (PMID 32123248, 2020). "Second, although beyond the scope of this study, the disease relevance of the finding that Casp-2-mediated Δtau314 production triggers cognitive impairment needs to be further validated." (PMID 32123248, 2020). "In addition, we showed that Δtau314 proteins are derived from all six tau splicing isoforms, that levels of both Casp2 and Δtau314 proteins are higher in cognitively impaired than in normal individuals, and that levels of Δtau314 proteins are moderately predictive of cognitive impairment." (PMID 32123248, 2020). "Cleavage of tau by Casp2 promotes the mislocalization of tau to dendritic spines leading to a reduction in postsynaptic AMPA receptors and excitatory neurotransmission, which suggests a mechanism of the synaptic dysfunction underlying cognitive impairment in LBD." (PMID 31362787, 2019). "In humans, alteration of caspase-2 initiated apoptosis (resulting from disruption of the PIDDosome) during nerve growth factor mediated proliferation of synaptic contacts may lead to inappropriate synaptic pruning that results in cognitive impairment." (PMID 22279524, 2012). "Intriguingly, recent reports suggest that, indeed, caspase-2-dependent generation of Δtau314 is also responsible for the cognitive deficits seen in Lewy body disease, non-dementia Parkinson’s disease as well as Huntington’s disease." (PMID 32415279, 2020). "Knocking-out Casp2 in YAC128 mice ameliorated cognitive deficits, although neurodegeneration was not affected." (PMID 31362787, 2019).
hepatocellular carcinoma (7 papers, 2019 to 2026). A malignant tumor that arises from hepatocytes. "We found that caspase-2 loss promotes early-onset hepatocyte hyperpolyploidy, accompanied by progressive liver inflammation, fibrosis, oxidative liver damage, ferroptosis, and higher incidence of spontaneous hepatocellular carcinoma in aged animals." (PMID 41477850, 2026). "Significance is determined by chi-square test: for liver carcinoma incidence, [Casp2+/+ versus Casp2C320S: χ2(1, N = 44) = 10.351, **P = 0.0013]." (PMID 41477850, 2026). "To further assess the possible role of caspase-2 in ferroptosis in liver cells, we used small interfering RNA (siRNA) to knockdown CASP2 in Huh7 hepatoma cells and then induced ferroptosis with either erastin or RSL3, a small-molecule inhibitor of GPX4." (PMID 41477850, 2026). "This is consistent with recent studies uncovering a key role of caspase-2 in lipotoxicity-induced apoptosis in hepatocytes, promoting the development of non-alcoholic steatohepatitis (NASH) that evolves into hepatocellular carcinoma." (PMID 39543123, 2024). "The tumor suppressor role of caspase-2 was also apparent in a diethylnitrosamine-induced mouse hepatocellular carcinoma (HCC) model, where at 10 months of age, all caspase-2-knockout animals developed malignant HCC, whereas the WT animals showed only adenomas and rarely HCC94." (PMID 33854186, 2021). "Probing the Provisional Liver Hepatocellular Carcinoma TCGA data set we found that CASP2 and PIDD1 transcript levels are significantly upregulated in human HCC across all disease stages." (PMID 33225610, 2020).
Huntington disease (7 papers, 2011 to 2023). Huntington disease (HD) is a rare neurodegenerative disorder of the central nervous system characterized by unwanted choreatic movements, behavioral and psychiatric disturbances and dementia. "Loss of caspase-2 was shown before to restore memory and other cognitive defects in a mouse model for Huntington’s disease, further supporting these findings." (PMID 32415279, 2020). "Expression of a catalytically inactive caspase-2 inhibited cleavage of HTT and reduced cell death, suggesting that caspase-2 may participate in cell death associated with neurodegeneration caused by Huntington’s disease." (PMID 33425918, 2020). "In addition to AD, caspase-2 is also involved in Huntington’s disease (HD)." (PMID 36129947, 2022). "Moreover, mice lacking CASP2 are protected from behavioral changes in a model of Huntington's disease." (PMID 37646198, 2023).
acute myeloid leukemia (6 papers, 2009 to 2022). Acute myeloid leukemia (AML) is a group of neoplasms arising from precursor cells committed to the myeloid cell-line differentiation. "Deficient caspase-2 activation has been observed in gastric cancer, and acute myeloblastic leukemias." (PMID 19714247, 2009). "4f downregulated NRF2 protein, had a profound growth-inhibitory effect on all three acute myeloid leukemia (AML) cell lines tested (THP-1, HL-60 and U937), and induced apoptosis, which was evidenced by flow cytometry, caspase-2 cleavage and PARP cleavage." (PMID 34384473, 2021). "As siRNA transfection per se induces HLA expression in THP-1 cells; caspase-2 expression was suppressed by shRNA in the acute monocytic leukemia THP1 and the acute myeloid leukemia OCI-AML2 cell lines." (PMID 29362422, 2018). "Finally, it was observed that the caspase-2-RFXANK interaction occurred in the cytoplasmic compartment, as verified by co-IP of endogenous caspase-2 using a specific RFXANK antibody and fractionated acute myeloid leukemia OCI-AML2 cell lysates." (PMID 29362422, 2018).
bladder cancer (6 papers, 2014 to 2024). "Researchers determined miR-708-5p’s contribution to bladder carcinoma progression is through targeting of caspase-2." (PMID 29050362, 2017). "A miR-708-5p inhibitor promoted apoptosis in vitro, and caspase-2 expression negatively correlated with miR-708-5p expression in bladder carcinoma patients." (PMID 29050362, 2017). "Among the up-regulated miRNAs miR-708-3p, which showed the highest fold change regulation, was reported in promoting the development of bladder carcinoma via direct repression of Caspase-2." (PMID 26645573, 2015).